ALK (ALK receptor tyrosine kinase)
Diseases named in the same sentence as ALK in open-access papers (continued):
Sharing a sentence is not in itself a finding about the gene and the disease.
cancer (continued). "The findings of this case report introduce a novel strategy for treating ALK-positive EIMS that utilizes ensartinib, a drug with previously demonstrated success in the treatment of ALK-positive cancer." (PMID 37869075, 2023). "Lorlatinib is used when cancer cells become resistant to drugs such as ceritinib, alectinib, crizotinib, or other ALK inhibitors." (PMID 37901797, 2023). "ALK inhibitors have revolutionized the management of cancers with ALK rearrangement abnormalities, improving PFS and OS in patients compared with chemotherapy." (PMID 37894307, 2023). "This study using 2017-2019 data from the National Taiwan Cancer Registry database found that among patients who received first-line ALK-TKI treatment, the median OS was shorter among smokers than among never-smokers." (PMID 37007097, 2023). "Crizotinib, for instance, was initially developed as an MET inhibitor, but later it was found to be even more efficient in cancers with ALK rearrangements." (PMID 36839989, 2023). "Pulmonary adenocarcinomas (pADCs) with an ALK rearrangement are a rare cancer subtype, necessitating comprehensive molecular investigations to unravel their heterogeneity and improve therapeutic strategies." (PMID 37511126, 2023). "ALK rearrangements/fusions are particularly important in cancer because they are pharmacologically tractable." (PMID 37773318, 2023). "A group that has often been identified as a major contributor to fusions, as well as cancers driven by other mutations, is the RTKs, especially the FGFR and NTRK subfamilies, as well as RET and ALK." (PMID 37509339, 2023). "We present several case studies with varying stages of cancer development (I−III), mutation status (EGFR, ALK), and biomarker expression based on a three-gene panel (CD133, KRT19, and MUC1)." (PMID 36900350, 2023). "ALK and LTK receptors are implicated in the development of numerous cancers, and targeted inhibition of their signaling pathways can offer therapeutic benefits." (PMID 37892172, 2023). "As in adults, more aggressive cancer behavior is expected in cases harboring p.V600E or other BRAF point mutations or BRAF-like fusions (e.g., RET/PTC1, NTRK3/ETV6, ALK rearrangements), although these correlations remain unconfirmed in children." (PMID 37046700, 2023). "Types and frequencies of different ALK alterations seen in cancer have been tabulated in 1,2,20–22,34,36,52,63,66,70–90." (PMID 37773318, 2023). "It is evident from the volcano plot that highly mutated genes MUC4, MUC16, CIITA, and ALK are mutated and overexpressed, of which ALK and CIITA are cancer census genes, whereas NCOR2 a transcriptional corepressor was mutated and downregulated." (PMID 37091785, 2023). "Anaplastic lymphoma kinase (ALK) alterations (activating mutations, amplifications, and fusions/rearrangements) occur in ~3.3% of cancers." (PMID 37773318, 2023). "More strikingly, the combination of ETV6 and ALK can also be extrapolated to multi‐cancer diagnostics in plasma and was validated in an independent cohort." (PMID 37649244, 2023). "focussed on understanding why ALK+ NSCLC cancers are immune cold and making them more receptive to ICIs using a vaccine‐based approach." (PMID 37795653, 2023). "In cancers covering NSCLC, ALK activation occurs through fusion gene formation, the preliminary actuating mutation in ALK." (PMID 36845553, 2023). "NSCLC is one of the cancers in which ALK gene fusions/rearrangements have been especially well recognized, with ~3–7% of cases affected." (PMID 37773318, 2023). "TKIs are effective against ALK fusion protein-driven cancers, but resistance and relapse usually occur after initial remission." (PMID 37892172, 2023). "Several trials have therefore addressed possible pan-cancer indications for ALK inhibitors, e.g., Genentech Mypathway trial (NCT02091141) and the phase 2 TAPISTRY platform study (NCT04589845)." (PMID 37773318, 2023).
cancer (continued). "ALK+ ALCL can be distinguished from other cancer types by a chromosomal translocation involving ALK, leading to the expression of both ALK protein and CD30 proteins." (PMID 37443818, 2023). "Perhaps due to ongoing genomic instability and compromised DNA repair mechanisms in cancer cells, The ALK gene is also subject to large structural variations called chromosomal rearrangements." (PMID 36734129, 2023). "The cellular and in vivo activities of ALK inhibitors were compared in engineered cancer-derived cell lines and in mice xenograft models, respectively." (PMID 37036582, 2023). "The ALK locus is particularly prone to chromosomal fusions, and this appears to play a role in both cancer development and evolution." (PMID 37892172, 2023). "Small compounds inhibiting SHP2 and PROTACs are being developed, and 11 allosteric SHP2 inhibitors (such as PD-1, MEK, RTK, ERK, BRAF, and ALK) are undergoing clinical evaluation for cancer treatment." (PMID 38001644, 2023). "It is now known that ALK translocations involve different fusion partners across and within cancers." (PMID 37773318, 2023). "In general, this novel method holds great potential to improve clinically relevant gene fusion detection for higher applicability of modern cancer therapies targeting ALK, ROS1, RET, and other gene fusions." (PMID 37300660, 2023). "By uncovering the spatially resolved biology of ALK-rearranged tumors, we hope this work will enhance our biological understanding and improve therapeutic efforts for this cancer type." (PMID 37511126, 2023). "Third, in cluster C, we observed changes in acetylation of transcriptional regulatory proteins (e.g., histones) that are suggestive of widespread transcriptional down-regulation in response to TKIs in both EGFR- and ALK-driven cancer cells." (PMID 36996232, 2023). "BCL2-related protein A1 (BCL2A1) is a member of the BCL-2 protein family, and its related pathways include apoptosis, autophagy, and ALK signaling in cancer." (PMID 37056387, 2023). "Crizotinib is a first-generation, oral, small-molecule ALK-TKI that was FDA approved in 2011 to treat cancers expressing EML4-ALK gene fusions." (PMID 36734129, 2023). "Rearrangements in the ALK gene can result in the abnormal production of the ALK protein, leading to increased growth and spread of cancer cells." (PMID 37901797, 2023). "Crizotinib, an anti-cancer medication through inhibiting anaplastic lymphoma kinase (ALK) and c-ros oncogene 1 (ROS1), has already been approved for the treatment of NSCLC." (PMID 36834736, 2023). "We next investigated the biochemical mechanisms by which the drug combination (alectinib with SHP099) reduced the growth of ALK+ cancer cells using Western blotting." (PMID 37339995, 2023). "Another HumKI having the amimopyrimidine moiety that has been evaluated for its antimicrobial activity against S. aureus is Ceritinib (compound 7), a tyrosine kinase inhibitor used in cancer treatment to inhibit anaplastic lymphoma kinase (ALK)." (PMID 37760715, 2023). "The data indicated activation of pathways that are known to promote cancer cells survival such as autophagy, the anaplastic lymphoma kinase (ALK) as well as TGFβ signaling, as shown in." (PMID 37123244, 2023). "Our results thus far suggested that alectinib, a therapy targeted toward ALK+ cancer cells, induced rapid and dramatic changes in the proteolytic activity of presumably ALK- vascular cells within the TME." (PMID 36192379, 2022). "ALKAL2, also named augmentor-α (AUG-α) or FAM150b, was first described in the adrenal gland and the retina, where its signaling through ALK and LTK receptors has been implicated in autoimmunity, neurodevelopment, and cancer." (PMID 35608912, 2022). "Ensartinib is a specific ALK TKI that is cytotoxic against a wide variety of cancer cell lines, including crizotinib-resistant cancer cell lines known to harbor ALK fusions or point mutations." (PMID 35565470, 2022).
cancer (continued). "Since then, many small-molecule PROTACs have been developed to fight cancer by degrading ALK, such as MS4077 and MS4078, TD-004, etc." (PMID 36557960, 2022). "Nowadays, the development of ALK inhibitors (ALK-i) has changed the treatment landscape of cancer patients with ALK alterations, as demonstrated by the dramatic and often prolonged responses to treatment achieved in patients affected by metastatic NSCLC." (PMID 35409355, 2022). "Among them, the optimal compound 10f featuring a flexible side-chain exhibited good potency on ALK-positive cancer cell lines." (PMID 36100230, 2022). "As a basis for the researchers’ involvement with the tyrosine kinase as a specific target in cancer treatment, the ALK fusion protein was created." (PMID 35956900, 2022). "Compound 12a exhibited good inhibitory activities against ALKwt or HDAC1 enzymes and synergistically inhibited proliferation of ALK-driven cancer cells via inducing cell apoptosis and cell cycle arrest." (PMID 36100230, 2022). "Altogether, the protein expression analysis confirmed enrichment of FOXP3-positive cells in ALK-positive cancer and depletion of CD8-postive cells in EGFR-positive cancer." (PMID 34125345, 2022). "This is a vaccine treatment design based on specific CTLs against EML4-ALK positive cancer cells, and further research and analysis are still required in order to realize the application of this type of vaccine in ALK positive NSCLC patients." (PMID 36591504, 2022). "As observed with other targeted therapies, resistance to ALK inhibitors frequently occurs in ALK-driven cancer." (PMID 35689207, 2022). "In this regard, very recently, it has been proven that ADRN-to-MES reprogrammed NB cells can escape from ALK targeted therapy, disclosing that NB cancer cells with an undifferentiated phenotype can mediate resistance to ALK inhibitors." (PMID 35277192, 2022). "The constitutively activated ALK fusion gene promotes cancer development by initiating some oncogenic pathways including MAPK, PI3K-Akt, JAK-STAT, and PLCγ." (PMID 35062949, 2022). "Cytotoxic cells, CD8+ T cells and exhausted CD8+ T cells were lower in EGFR-positive cancer compared to treatment-naïve ALK/EGFR-negative cancer (FC = − 2.2, p = 4.1E-05; FC = − 2.0, p = 0.01 and FC = − 1.7, p = 0.0082)." (PMID 34125345, 2022). "Although ALK fusions with different partners are found in various cancers, the CARS1-ALK fusion has been reported only in IMT39." (PMID 35501376, 2022). "Further, in most ALK rearranged malignancies, the ALK kinase expressed by the ALK gene is normally located within cancer cells, but the proteins expressed by ALK fusion partners are often located extracellularly." (PMID 36591504, 2022). "The study was carried out to investigate the prognostic value of Beclin 1, EGFR and ALK for this cancer." (PMID 36401689, 2022). "After 10 days-culture in presence of ALK-TKIs, the residual cancer cells were markedly reduced with nearly eliminated by shSTAT3." (PMID 35228642, 2022). "Mechanistically, ALK mediated cancer growth inhibition depended on the ALK mRNAs copy number, therefore these results call for a careful evaluation of the ALK full-length abundance in CRC specimen, to schedule the right treatment." (PMID 35351152, 2022). "It is well known that ALK gene rearrangement (fusion), mutation, amplification and alternative splicing events can lead to a variety of cancers, and ALK gene rearrangement is the most common type in various types of cancer." (PMID 36591504, 2022). "As is well known, the AKT/mTOR pathway is one of the important signaling pathway downstream of ALK, and it plays an important role in cell proliferation and survival in cancer." (PMID 35459209, 2022).
cancer (continued). "Compared with adjacent normal tissue, Beclin 1 expression was elevated in the cancer tissue significantly; assessments of EGFR and ALK mutations showed that out of the 480 patients, 233 (48.5%) and 75 (12.6%) patients had EGFR and ALK mutations." (PMID 36401689, 2022). "The FDA has approved a number of mutations for cancer screening or cancer assaying, including mutations in the BRCA1 and BRCA2 genes for ovarian cancer, ALK rearrangements for NSCLC, and alterations in the PIK3CA gene for breast cancer patients." (PMID 35053452, 2022). "Compound 12a which possessed good inhibitory potency against ALKwt and HDAC1, exhibited stronger antiproliferative activity than Ceritinib on ALK positive cancer cell lines though inducing cell apoptosis and cell cycle arrest in vitro and in vivo." (PMID 36100230, 2022). "ALK-positive cancers are characterized by gene fusion that induces overexpression or constitutive receptor activation." (PMID 35608912, 2022). "ALK-mediated phosphorylation of ATIC can rescue cancer cells from cell death induced by antifolate agents." (PMID 35205374, 2022). "Follow-up transcriptomic profiling unearthed a potential mechanism of communication, mediated by PDGF and CXCL12, between ALK+ cancer cells, endothelial cells, and pericytes." (PMID 36192379, 2022). "The accelerated approval of the first anaplastic lymphoma kinase (ALK) TKI crizotinib increases the paradigm of cancer drugs development." (PMID 35267628, 2022). "Relevant studies have demonstrated the existence of a precursor pool of anti ALK CD8+T lymphocytes in cancer patients." (PMID 36591504, 2022). "The latest NSCLC guideline 2021 V2 edition issued by the national comprehensive cancer network (NCCN) indicated that genes associated with targeted therapy of NSCLC include EGFR, KRAS, ALK, ROS1, MET, BRAF, RET, and NTRK." (PMID 35227278, 2022). "There are few mutated antigens that have been discovered where the mutated peptide is shared across cancer types, and the most common reported shared mutations were KRAS, NRAS, BCR-ABL translocation, ETV6, NPM/ALK, and ALK." (PMID 35342400, 2022). "Using the protect bioinformatics technology combined with animal experiments, it is possible to develop more therapeutic vaccines against ALK positive NSCLC, which also needs further exploration for other types of ALK mutant cancers." (PMID 36591504, 2022). "ALK is generally poorly expressed in normal adult tissues, making it a highly promising molecular target for cancer therapy." (PMID 35351152, 2022). "K-RAS, epidermal growth factor receptor (EGFR) and anaplastic lymphoma kinase (ALK) can induce PD-L1 expression in cancer cells." (PMID 36499710, 2022). "We established a strategy to identify ALK-specific 5-mC changes from cfDNA and demonstrated the suitability of the identified markers for cancer detection, prognosis, and therapy monitoring." (PMID 36461127, 2022). "The present study demonstrates that crizotinib attenuates cancer metastasis by ALK/MET/RON/ROS1-independent inhibition of TGFβ signaling in NSCLC cells." (PMID 35999455, 2022). "Not only was the efficacy of ALK inhibitors increased, but the proliferative capacity of the cancer cells was decreased whilst the apoptotic rate was increased." (PMID 35884511, 2022). "As ALK+ NSCLC is a gene fusion-driven cancer, tyrosine kinase inhibitors (TKIs) have been developed to treat this unique disease." (PMID 35463328, 2022). "Pan-cancer drug target RTK fusions also include the moieties of ALK, ERBB2, FGFR1-4, MET, RET, and ROS1 genes." (PMID 36009413, 2022). "Considerable research has focused on elucidating the mechanisms behind EML4-ALK fusion-driven cancer progression, largely due to the fact that they are the most common ALK rearrangement in NSCLC." (PMID 35884511, 2022). "In this study, we showed that cancer-derived changes of the methylome can be detected in cfDNA samples of ALK-positive NSCLC patients." (PMID 36461127, 2022).
cancer (continued). "Of further compelling interest is a phase II trial in ctDNA-positive postoperative cases incorporating a personalized cancer vaccine with atezolizumab postchemotherapy in again a non-ALK group (NCT04267237)." (PMID 36003760, 2022). "Small-molecule ALK tyrosine kinase inhibitors are very effective against a group of cancers defined by chromosomal rearrangements involving the anaplastic lymphoma kinase (ALK) gene." (PMID 36145589, 2022). "Tyrosine kinase inhibitors (TKI), molecular-targeted drugs, inhibit specific oncogenic drivers, such as the epidermal growth factor receptor (EGFR) and anaplastic lymphoma kinase (ALK), which trigger cancer evolution." (PMID 36434641, 2022). "Next, we identified cancer-derived differentially methylated regions (DMRs) from cfDNA at ‘5-mC background’-depleted sites by comparing ALK-positive patients to healthy controls." (PMID 36461127, 2022). "In discovery of novel HDAC inhibitors for the treatment of cancer, the 5-chloro-4-((substituted phenyl)amino)pyrimidine structure often used in the ALK inhibitors was introduced in the design of HDAC inhibitors." (PMID 35833370, 2022). "Anaplastic lymphoma kinase (ALK) has been identified as an oncogenic driver in several cancers especially in NB and is considered a critical contributor for tumorigenesis and a promising therapeutic target of NB." (PMID 35721107, 2022). "Epidermal growth factor receptor (EGFR) and anaplastic lymphoma kinase (ALK) are two paradigms of cancer driven genes that provide highly efficient therapeutic targets." (PMID 35876652, 2022). "ALK signaling is activated in cancer cells primarily through three mechanisms: gene fusions, gene amplification, and activating point mutations." (PMID 35463328, 2022). "This epidemiologic distribution of ALK rearrangement was confirmed in more recent studies, all representing by striatin (STRN)-ALK fusion, an extremely rare ALK rearrangement reported in only 56 cancers of different organs." (PMID 35223506, 2022). "The bone marrow fibroblasts highly uptake ALK+ ALCL-derived exosomes and acquire a cancer-associated fibroblast (CAF) phenotype." (PMID 35740600, 2022). "Firstly, the results obtained for the complete group of ALK/EGFR-negative tumors stayed correct for the subgroup of treatment-naïve tumors: Tregs were higher in ALK-positive cancer compared to treatment-naïve ALK/EGFR-negative cancer (FC = 2.3, p = 0.00015)." (PMID 34125345, 2022). "Similar patterns have been observed in other kinases involved in fusions in cancer such as ALK, ROS, and TRK15–17." (PMID 35304457, 2022). "The three generations of ALK-TKIs greatly enriched the therapeutic regimens of ALK-positive cancer patients, but drug selection needs to consider many factors, among which the toxicity profile was one of the critical considerations." (PMID 35370632, 2022). "As aberrant activation of ALK is involved in malignancy, research has focused on developing specific inhibitors for cancer therapy, and many of them are now used in clinical practice." (PMID 35608912, 2022). "All CBs related to carcinoma NOS were adequate for ALK, ROS1 and PD‐L1 assessment and also molecular profiling." (PMID 35868633, 2022). "Two patients received a diagnosis of carcinoma NOS, and all samples were adequate for ALK, ROS1 and TPS PD‐L1 immunohistochemical assessment and molecular profiling." (PMID 35868633, 2022). "All four CB results obtained from carcinoma NOS were adequate for ALK, ROS1 and PD‐L1 assessment and molecular profiling." (PMID 35868633, 2022). "Elevated protein expression of ROCK1 and ALK has a strong prognostic value for cancers in humans as well as EMN in equines." (PMID 34199079, 2021). "This fusion allows cancer transformation by activating downstream reactions in the ALK signaling pathway." (PMID 33557176, 2021). "‘VariO:0437 alternatively initiated mRNA’ of ALK receptor tyrosine kinase (ALK) is frequent in melanomas and appears also in some other cancer types." (PMID 32951567, 2021).